MIR149 (microRNA 149)
Synonyms: hsa-mir-149; MIRN149; mir-149
Gene: MicroRNA gene on chromosome 2 (240,456,001 to 240,456,089, forward strand). Ensembl gene ENSG00000207611.
Gene Ontology:
Biological process: miRNA-mediated post-transcriptional gene silencing
Cellular component: RISC complex
Diseases named in the same sentence as MIR149 in open-access papers:
MIR149 is named in the same sentence as 6 diseases in open-access papers, as found by Europe PMC text mining. Sharing a sentence is not in itself a finding about the gene and the disease. The quoted sentences say what the papers report.
breast carcinoma (2 papers, 2021 to 2023). "MIR149 has previously been linked to the risk of multiple cancers, including colorectal, liver, and breast cancer." (PMID 36901860, 2023). "MIR149 plays an important part in tumorigenesis and tumor progression, and its downregulation promoted the metastatic dissemination of tumor cells by supporting aberrant Rac activation in breast cancer." (PMID 33403044, 2021).
glioblastoma (1 paper, 2021). The most malignant astrocytic tumor (WHO grade IV). "We found previously uncharacterized miRNA genes in pediatric CNS tumors, including MIR149, MIR214, MIR574 and MIR765, apart from one study that reported MIR595 upregulation in glioblastoma compared to control cells, in vitro." (PMID 34204289, 2021).
cancer (1 paper, 2021). A tumor composed of atypical neoplastic, often pleomorphic cells that invade other tissues. "Pan-cancer analysis showed that MIR129-2, MIR149, MIR152, MIR150, MIR34B, and MIR34C were downregulated in at least four types of cancer, and MIR150 had a protective role against death in most types of cancer." (PMID 33403044, 2021).
CNS tumors (1 paper, 2021). "In cluster 2, MIR149, MIR214, MIR574, MIR595 and MIR765 were globally down-regulated across all CNS tumor samples; ten miRNA genes were also found globally down-regulated in >90% of all samples." (PMID 34204289, 2021).
MIR149 also shares sentences with these, for which no sentence is quoted: rheumatoid arthritis (1 paper); tumor (1).